IP6K2 (inositol hexakisphosphate kinase 2)
Description:
Converts inositol hexakisphosphate (InsP6) to diphosphoinositol pentakisphosphate (InsP7/PP-InsP5).
Synonyms: InsP6K2; PiUS; IHPK2
Tractability: Small molecule: a high-quality ligand is known. PROTAC: ubiquitination databases record sites on it; a small molecule that binds it is known.
Target class: Enzyme; Transferase
Gene: Protein-coding gene on chromosome 3 (48,688,003 to 48,740,353, reverse strand). Ensembl gene ENSG00000068745.
Subcellular location: Nucleus
Subcellular location (Human Protein Atlas): Nucleoli fibrillar center; Cell Junctions; Nucleoplasm
Pathways (Reactome):
Immune System: Interferon alpha/beta signaling
Metabolism: Synthesis of IPs in the nucleus
Gene Ontology:
Molecular function: flavonoid binding; inositol hexakisphosphate 5-kinase activity; inositol hexakisphosphate kinase activity; protein binding; protein-containing complex binding; diphosphoinositol pentakisphosphate kinase activity; diphosphoinositol tetrakisphosphate kinase activity; inositol 5-diphosphate pentakisphosphate 5-kinase activity; inositol-1,3,4,5,6-pentakisphosphate kinase activity; kinase activity
Biological process: cellular response to flavonoid; inositol phosphate metabolic process; negative regulation of cell growth; phosphatidylinositol phosphate biosynthetic process; positive regulation of apoptotic process; positive regulation of peptidyl-serine phosphorylation; positive regulation of protein K48-linked ubiquitination; positive regulation of protein serine/threonine kinase activity; protein stabilization; inositol phosphate biosynthetic process; organophosphate biosynthetic process; phosphatidylinositol metabolic process
Cellular component: fibrillar center; nucleoplasm; nucleus; cytoplasm
Genetic constraint (gnomAD): Loss-of-function variants: 8 observed, 37.51 expected, observed/expected ratio (o/e) 0.21, 90% interval 0.12 to 0.38. The upper end of that interval is the gene's LOEUF score, 0.38, which puts it in group 1 of 6, group 1 being the genes least tolerant of losing a copy. Missense variants: 311 observed, 517.73 expected, observed/expected ratio (o/e) 0.6, 90% interval 0.55 to 0.66. Synonymous variants: 191 observed, 197.55 expected, observed/expected ratio (o/e) 0.97, 90% interval 0.86 to 1.09.
Homologues: Orthologues: chimpanzee IP6K2 (100% identical), macaque IP6K2 (100% identical), dog IP6K2 (97% identical), mouse Ip6k2 (97% identical), pig IP6K2 (96% identical), rat Ip6k2 (96% identical), rabbit IP6K2 (96% identical), guinea pig IP6K2 (95% identical), tropical clawed frog ip6k2 (80% identical), zebrafish ip6k2a (65% identical), zebrafish ip6k2b (63% identical), Drosophila melanogaster Ip6k (35% identical), and 3 more. Paralogues in human: IP6K1 (48% identical), IP6K3 (43% identical), IPMK (19% identical), ITPKB (18% identical), ITPKC (17% identical), ITPKA (15% identical).
Diseases named in the same sentence as IP6K2 in open-access papers:
IP6K2 is named in the same sentence as 31 diseases in open-access papers, as found by Europe PMC text mining. Sharing a sentence is not in itself a finding about the gene and the disease. The quoted sentences say what the papers report.
bladder cancer (2 papers, 2022 to 2023). "We found that IP6K2 knockdown promotes bladder cancer cell proliferation and colony formation." (PMID 38017469, 2023). "Effect of IP6K2 and PLA2G2F on cell proliferation in vitro was explored to determine their role in bladder cancer cell proliferation." (PMID 38017469, 2023). "IP6K2 and PLA2G2F expression in bladder cancer and adjacent tissues was detected using RT-qPCR." (PMID 38017469, 2023).
cognitive decline (2 papers, 2024 to 2025). "Further analysis in prodromal cases revealed that subjects with TRIM40 heterozygous alleles (C/T) alleles experienced faster motor and cognitive decline, while those with IP6K2 homozygous G alleles showed greater depression over 12 years in prodromal cases." (PMID 40542411, 2025). "IP6K2 was associated with cognitive impairment prior to the onset of motor symptoms and FGF20 was associated with rapid cognitive decline after the onset of motor symptoms in PD." (PMID 38988604, 2024). "In this study, we found that IP6K2 rs12497850 was associated with cognitive impairment at the time of motor symptoms onset, and FGF20 rs591323 was associated with more rapid cognitive decline after motor symptoms onset." (PMID 38988604, 2024).
colon carcinoma (2 papers, 2019 to 2023). "We used CRISPR and the human colon carcinoma line HCT116 to create a cell line truly devoid of PP-IPs by disrupting both IP6K1 and IP6K2." (PMID 31186349, 2019).
colorectal cancer (2 papers, 2017 to 2022). A primary or metastatic malignant neoplasm that affects the colon or rectum. "Knockdown of IP6K2 impairs apoptosis in colorectal cancer cells, and its deletion or low expression is associated with adverse clinical outcomes in aerodigestive tract carcinoma and breast cancer." (PMID 35246212, 2022).
glioma (2 papers, 2021 to 2022). A benign or malignant brain and spinal cord tumor that arises from glial cells (astrocytes, oligodendrocytes, ependymal cells). "RT-PCR, EdU and transwell assays were conducted to observe the effect of IP6K2 on glioma cell proliferation, migration and invasion." (PMID 35156508, 2022). "Using bioinformatics analysis, RT-PCR, and dual luciferase reporter gene assay, the potential role of the LINC00467/miR-339-3p/IP6K2 regulatory axis in glioma was verified." (PMID 35156508, 2022). "We then conducted EdU and Transwell experiments to measure the effect of the LINC00467/miR-339-3p/IP6K2 regulatory axis on the proliferation, migration, and invasion of glioma cells." (PMID 35156508, 2022). "In this study, we used bioinformatics analysis and discovered that IP6K2 is highly expressed in glioma tissues." (PMID 35156508, 2022). "This study aimed to demonstrate the expression level, biological function and potential mechanism of IP6K2 in glioma." (PMID 35156508, 2022). "To probe the biological effects of IP6K2 in gliomas, we used shRNAs or overexpression plasmids (OE) to inhibit or overexpress IP6K2 in U87 and U251 cells, and used RT-PCR to verify the transfection efficiency." (PMID 35156508, 2022). "This study aimed to explore the biological role of the LINC00467/miR-339-3p/ inositol hexakisphosphate kinase 2 (IP6K2) regulatory axis in glioma." (PMID 35156508, 2022). "We measured the expression of IP6K2 in 30 glioma tissue samples and 30 normal control tissues using RT-PCR." (PMID 35156508, 2022). "Further, IP6K2 overexpression significantly promoted glioma tumor growth in vivo, which is consistent with our in vitro results." (PMID 35156508, 2022). "The Cancer Genome Atlas (TCGA), Oncomine databases and reverse transcription‐quantitative PCR (RT‐qPCR) were used to analyze IP6K2 expression in glioma." (PMID 35156508, 2022). "Further, Western blot results confirmed that the protein expression level of IP6K2 in glioma tissues was also significantly increased." (PMID 35156508, 2022). "Overall, this study verified the function and mechanism of the LINC00467/miR-339-3p/IP6K2 regulatory axis in glioma, which might provide a novel insight for glioma diagnosis and therapy." (PMID 35156508, 2022). "Overall, LINC00467 could upregulate IP6K2 by binding to miR-339-3p and promote the proliferation, migration, and invasion of glioma cells." (PMID 35156508, 2022). "In vitro and in vivo experiments indicated that IP6K2 overexpression could promote the proliferation, migration, and invasion of glioma cells." (PMID 35156508, 2022). "IP6K2 is a tumor-promoting gene that is highly expressed in gliomas, but its possible molecular mechanism is unknown." (PMID 35156508, 2022). "Therefore, this study aimed to explore the possible biological effects and therapeutic potential of LINC00467/miR-339-3p/IP6K2 in glioma." (PMID 35156508, 2022). "Furthermore, we used RT-PCR to determine the expression level of IP6K2 in 30 glioma tissue samples and normal control tissues." (PMID 35156508, 2022). "The results showed that IP6K2 was up-regulated in glioma tissues and cell lines." (PMID 35156508, 2022). "IP6K2 in glioma cell lines was also remarkably higher than that in normal control cells." (PMID 35156508, 2022). "The LINC00467/miR-339-3p/IP6K2 regulatory axis might thus be a biomarker and potential therapeutic target in glioma." (PMID 35156508, 2022). "Further bioinformatics analysis and in vitro assays revealed that LINC00467 could promote IP6K2 expression by binding to miR-339-3p and promote the malignant progression of glioma." (PMID 35156508, 2022). "The results showed that IP6K2 expression was significantly increased in glioma tissues." (PMID 35156508, 2022). "OE-IP6K2 significantly promoted the expression of IP6K2 in glioma cells." (PMID 35156508, 2022). "The results indicated that the expression of IP6K2 in glioma tissues was significantly higher." (PMID 35156508, 2022).
glioma (continued). "In this study, we found that IP6K2 expression is significantly increased in gliomas upon analyzing bioinformatics databases, but its biological effects and potential molecular mechanisms remain unclear." (PMID 35156508, 2022). "This study preliminarily proved that LINC00467 might boost the proliferation, migration, and invasion of glioma cells by binding with miR-339-3p to promote the expression of IP6K2." (PMID 35156508, 2022). "In vivo and in vitro cell experiments showed that overexpression of IP6K2 could significantly promote the growth and metastasis of gliomas, indicating that IP6K2 might be involved in the malignant progression of gliomas as an oncogene." (PMID 35156508, 2022). "In this study, through a range of in vitro experiments and bioinformatics analyses, we preliminarily proved that LINC00467 might promote IP6K2 expression by binding with miR-339-3p to promote the proliferation, migration, and invasion of gliomas." (PMID 35156508, 2022). "Moreover, in our validation cohort, IP6K2 was elevated in patients with advanced stages of glioma (III + IV vs I + II, P = 0.009) and metastatic glioma (P = 0.026)." (PMID 35156508, 2022). "Moreover, the expression level of IP6K2 was correlated with the clinical features of glioma patients." (PMID 35156508, 2022). "The LINC00467/miR-339-3p/IP6K2 regulatory axis might be a potential therapeutic target for glioma." (PMID 35156508, 2022). "We hypothesized that IP6K2 could function as a vital role in the maglinant progression of glioma." (PMID 35156508, 2022). "Based on our previous study and results of assays, we demonstrated that LINC00467 was obviously up-regulated in glioma tissues and cell lines, and LINC00467 could sponge miR-339-3p to up-regulate IP6K2 expression in cytoplasm and promote glioma progression." (PMID 35156508, 2022).
lung adenocarcinoma (2 papers, 2022). A carcinoma that arises from the lung and is characterized by the presence of malignant glandular epithelial cells. "Furthermore, new candidate driver genes of lung adenocarcinoma, like PNCK and IP6K2 could also be found in this family." (PMID 35712480, 2022).
ovarian carcinoma (2 papers, 2020 to 2023). A malignant neoplasm originating from the surface ovarian epithelium. "In ovarian carcinoma cells, IP6K2 deletion confers protection against interferon alpha (IFNα)-induced cell death, whereas overexpression of IP6K2 enhances the apoptosis rate promoted by IFNα and/or γ-irradiation." (PMID 32992691, 2020). "Deletion of IP6K2 prevents apoptotic consequences of γ-irradiation or β-interferon addition to ovarian cancer cells, while overexpression of IP6K2 significantly raises cell death rate under the same conditions." (PMID 32992691, 2020).
Parkinson disease (2 papers, 2023 to 2024). A progressive degenerative disorder of the central nervous system characterized by loss of dopamine producing neurons in the substantia nigra and the presence of Lewy bodies in the substantia nigra and locus coeruleus. "We nominated candidate genes in each locus and identified novel pathways potentially involved in Parkinson’s disease, such as the inositol phosphate biosynthetic pathway (INPP5F, IP6K2, ITPKB and PPIP5K2)." (PMID 37804111, 2024).
carcinoma of the gastrointestinal (1 paper, 2020).
Cognitive impairment (1 paper, 2024). Abnormal cognition is characterized by deficits in thinking, reasoning, or remembering. "Multigenetic factors significantly associated with cognitive impairment at early stage of the disease (AUC = 0.950) with IP6K2 rs12497850 more evident, and a significantly faster decline (AUC = 0.831) within 5 years after motor onset, particularly in those carrying FGF20 rs591323." (PMID 38988604, 2024).
depression (1 paper, 2025). "The IP6K2 gene was linked to worse clinical progression, particularly higher depression levels in prodromal cases, and is known for its neuroprotective role in preventing PTEN-induced kinase 1 (PINK1)-mediated mitophagy in the brain." (PMID 40542411, 2025).
hepatocellular carcinoma (1 paper, 2020). A malignant tumor that arises from hepatocytes. "Ip6k3 is upregulated in NAFLD patients, whereas Ip6k1 and Ip6k2 expression directly correlate with hepatocellular carcinoma (HCC)." (PMID 32204420, 2020). "The expression of Ip6k1 correlates inversely with insulin sensitivity, whereas both Ip6k1 and Ip6k2 expression directly correlate with hepatocellular carcinoma (HCC)." (PMID 32204420, 2020).
invasive carcinoma (1 paper, 2016). A carcinoma that is not confined to the epithelium, and has spread to the surrounding stroma. "Our results upon feeding the same carcinogen to Ip6k1 knockout mice revealed that unlike IP6K2, the loss of IP6K1 protects them from invasive carcinoma, underlining the fact that IP6K1 and IP6K2 have distinct roles in carcinogenesis." (PMID 27140681, 2016). "However, unlike IP6K2, IP6K1 is essential for 4NQO-induced invasive carcinoma." (PMID 27140681, 2016).
liver cancer (1 paper, 2021). An epithelial or non-epithelial malignant neoplasm that arises from the liver. "The study provided evidence of differential alternative splicing of human leukocyte antigens (HLA)-A, HLA-C and inositol hexakisphosphate kinase 2 (IP6K2) that are associated with HBV and HCV liver cancer." (PMID 33530521, 2021).
cancer (9 papers, 2010 to 2023). A tumor composed of atypical neoplastic, often pleomorphic cells that invade other tissues. "Inositol hexakisphosphate kinase 2 (IP6K2), which has six exons in the canonical transcript, is known to be associated with cancer cell migration, invasion, and tumor metastasis, but it has not been established how this gene affects HCC development related with the three etiologies." (PMID 31856847, 2019). "IP6K2 is known to be associated with cancer cell migration, invasion, and tumor metastasis." (PMID 31856847, 2019). "CCK-8 assays demonstrated that IP6K2 knockdown significantly promoted cancer cell proliferation in 5637 and UM-UC-3 cells." (PMID 38017469, 2023). "Depletion of IP6K2 in various cancer cells (OVCAR3, HeLa, and HL60) protects cellular apoptosis in response to cisplatin, etoposide, and other various cytotoxic reagents." (PMID 32397291, 2020). "IP6K2 activity sensitizes a number of cancer cells, including OVCAR3, HeLa, HEK293, PC12, and HL60, to apoptosis." (PMID 32992691, 2020). "It is also likely that the effects of IP6K2 on cancer cells are disjointed, i.e., IP6K2 probably enhances apoptosis while increasing the acquisition of an invading/migrating phenotype." (PMID 32992691, 2020). "A number of studies suggest an essential role for IP6K2 in cell death, migration, cancer metastasis, and progression." (PMID 32992691, 2020). "IP6K2 KO mice show improved survival following irradiation, suggesting that IP6K2 is a key factor in sensitizing cancer cell death." (PMID 32397291, 2020). "Our study therefore uncovers similarities and differences in the roles of IP6K1 and IP6K2 in cancer progression, and we propose that an isoform-specific IP6K1 inhibitor may provide a novel route to suppress carcinogenesis." (PMID 27140681, 2016). "Expression levels of IP6K2 and PLA2G2F were significantly downregulated in cancer tissues compared with their expression levels in adjacent tissues." (PMID 38017469, 2023). "As observed in IP6K1-KO models, IP6K2-KO, too, reduces cell–cell adhesion, growth, spreading, metastasis, and FAK phosphorylation in cancer cells." (PMID 32992691, 2020). "Thus, our data reveal that like IP6K2, IP6K1 is also involved in early cytoskeleton remodeling events during cancer progression." (PMID 27140681, 2016). "However, IP6K2 also has an essential role in cancer cell apoptosis, and mice lacking this protein are more susceptible to the development of aerodigestive tract carcinoma upon treatment with the oral carcinogen 4-nitroquinoline-1-oxide (4NQO)." (PMID 27140681, 2016).
tumor (9 papers, 2012 to 2022). "IP6K2 may, therefore, act as a tumor suppressor in the initiation stage but contribute to metastatic spread by enacting EMT at later stages." (PMID 32992691, 2020). "Indeed, a number of results have clearly established that deletion of IP6K1 or IP6K2 reduces cell migration, while IP6K2-KO, quite paradoxically, reduces tumor volume." (PMID 32992691, 2020). "IP6K2 has been shown to promote tumor cell growth and migration by antagonizing liver kinase B1." (PMID 27140681, 2016). "The distinct functions of IP6K1 and IP6K2 in tumor development may also arise from their differential effects on cell proliferation, with IP6K2 knockout HCT116 cells exhibiting delayed growth, and IP6K1 depleted cells exhibiting no change in doubling time." (PMID 27140681, 2016). "IP6K2 has been reported to promote apoptosis, and yet also drives tumor growth and metastasis." (PMID 31051014, 2016). "We examined the relationship between ASE and SCNAs for two genes, IP6K2 and KIF1B, which have been previously identified as potential tumor suppressors located within the chromosome 3p and 1p deletion regions." (PMID 35246212, 2022). "The representative IHC images of normal/tumor and low/high grade tissues from HPA revealed that the degree of staining intensity of CD96, DDB1, IP6K2, PDCL3, TRIM38, and KCNJ15 were in correspondence with our predictions of coefficient." (PMID 34268106, 2021). "Although HCT116 cells lacking IP6K2 show reduced tumor development, mice lacking IP6K2 show accelerated development of invasive aerodigestive tract epithelial carcinoma upon being fed the oral carcinogen 4NQO." (PMID 27140681, 2016). "Recently, it was shown that HCT116 cells lacking IP6K2 display defects in cell adhesion and migration, resulting in reduced tumor growth and metastasis when these cells are implanted in immunocompromised mice." (PMID 27140681, 2016).
IP6K2 also shares sentences with these, for which no sentence is quoted: breast carcinoma (1 paper); cholangiocarcinoma (1); Crohn disease (1); esophageal carcinoma (1); glioblastoma (1); infection (1); kidney chromophobe (1); lung carcinoma (1); lung squamous cell carcinoma (1); neuroblastoma (1); Obesity (1); prostate adenocarcinoma (1); prostate carcinoma (1); renal cell carcinoma (1); stomach adenocarcinoma (1).